IL5 (interleukin 5)
Diseases named in the same sentence as IL5 in open-access papers (continued):
Sharing a sentence is not in itself a finding about the gene and the disease.
asthma (continued). "In addition to reduced type 2 cytokine protein levels in OVA‐driven asthma, diminished mRNA expression levels of Il‐5, Il‐13, and Il‐4 were observed in CD4‐enriched lung cells from LXRα−/−β−/− mice." (PMID 27621817, 2016). "Recently, asthma endotype cluster analysis followed by genotype or phenotype cluster analysis has achieved successful clinical results, including anti-IL-5 antibody therapy for persistent eosinophilic severe asthma and anti- IL-4 or anti-IL-13 antibody therapy for high-Th2-type severe asthma." (PMID 27965774, 2016). "Two different anti-IL-5 humanized monoclonal antibodies, mepolizumab and reslizumab, have been proven effective in this phenotype of asthma (recently they both came on the market in the United States), as well as an anti-IL-5 receptor alpha (IL5Rα), benralizumab." (PMID 27942351, 2016). "Based on previous findings, we hypothesized that IL-25 in asthma could promote the activation of nuocytes, and then in turn induce a large amount of IL-5 and IL-13 to enhance Th2 cytokine responses." (PMID 27617447, 2016). "Several mediators/modulators are involved in asthma pathogenesis and in hyperresponsiveness such as Th2 cytokines (IL-5, IL-4, and IL-13), IL-17, leukotrienes, nitric oxide, Rho kinase, cholinergic system, and others that were clearly evaluated in humans and animal models." (PMID 27445433, 2016). "IL-31 is a Th2 cytokine, to determine whether its serum concentration is correlated with other asthma related Th2 cytokines in asthma, we further measured the Th2 related cytokines IL-5, IL-13 and thymic stromal lymphopoietin (TSLP)." (PMID 26956917, 2016). "First, we aimed to identify the overall effect of anti-interleukin-5 therapy on asthma, the asthma severity and baseline asthma therapy varied among studies, so the population examined in this review was too heterogeneous to draw any conclusions about the general asthma population." (PMID 27875559, 2016). "Anti-interleukin-5 therapy may therefore be beneficial as adjunct asthma therapy, particularly in severe and eosinophilic asthma." (PMID 27875559, 2016). "Values of IL-5 were significantly increased in patients with intrinsic versus extrinsic asthma." (PMID 27275299, 2015). "‘IL‐13 and IL‐5 high responders’ were at much higher risk of HDM sensitization and asthma compared to all other classes, with 88% of children assigned to this class being sensitized and 28.5% having asthma." (PMID 26061524, 2015). "Therefore, biologic targeted therapies have been developed to target the specific molecular pathways to treat asthma, especially those targets at IL-4, IL-5, IL-13, and IgE." (PMID 26064160, 2015). "DA could dose-dependently inhibited ovalbumin-induced increases in total and eosinophil counts, IL-4, IL-5, and IL-13 levels in lavage fluid in a mouse asthma model." (PMID 26223251, 2015). "Compared to healthy control subjects, patients with asthma had significantly more percentages of eosinophils and neutrophils, IL-1RA, IL-1α, IL-1β, IL-2Rα, IL-5, IL-6, IL-7, IL-8, G-CSF, GROα (CXCL1), MIP-1β (CCL4), MIG (CXCL9), RANTES (CCL5) and TRAIL in their BAL fluids." (PMID 26011707, 2015). "For CRSwNPs, the presence of IL-5 and SE-Ig E but not S. aureus in tissue was associated with comorbid asthma." (PMID 26275068, 2015). "More than half (62.5%) of the patients with IL-5 and SE-IgE positive NPs had co-morbid asthma." (PMID 26275068, 2015). "Rho kinase may also be involved in eotaxin and cytokine (IL-5, IL-13) production and in secretion of matrix metalloproteinase – 9 (MMP-9), tightly associated with fibrosis in asthma and chronic obstructive pulmonary disease (COPD)." (PMID 26646719, 2015). "Th2-related cytokines (IL-5, IL-6, and IL-13) can contribute to the induction of asthma." (PMID 25658604, 2015).
asthma (continued). "Notwithstanding this potential limitation, this group might represent those that are at greatest risk and would warrant further eosinophil-specific therapy such as anti-IL-5, which would likely reduce the overall eosinophil burden as observed in asthma." (PMID 25007795, 2014). "IL-5 and IL-13 are classical Th2 cytokines, promoting B cell growth and maturation, activating eosinophil granulocytes, promoting the defense against parasites, in addition to playing active roles in asthma and allergy disorders." (PMID 24714360, 2014). "Persistence of eosinophilia in severe asthma could be a reflection of corticosteroidinsensitivity, and refractory asthma might respond to the use of anti-IL-5 therapy withmepolizumab." (PMID 25410844, 2014). "Hence, HDM-specific IL-5 T cell responses are the best predictor for the presence of asthma and atopy at the age at 8 years." (PMID 24875149, 2014). "One genotype combination EPHX1 113HH × IL5 −703CC showed a significant association with increased risk of nonallergic asthma in women (OR = 8.58; 95% CI 2.43–30.26; Padj = 0.001)." (PMID 24895604, 2014). "Wogonin may be applied as a preventive and therapeutic agent for IgE- and IL-5-mediated allergic disorders such as food allergy, atopic dermatitis, and asthma." (PMID 24566319, 2014). "Additionally, intrinsic asthma denoted by normal IgE and IL-4 levels, is associated with increased eosinophilia and IL-5 levels, compared to those with extrinsic asthma characterized by increased IL-5 and IL-4." (PMID 24971469, 2014). "In fact, the currently available anti-IL5 treatments are being considered beyond asthma management; especially in clinical complications with an underlying eosinophilic pathobiology such as hypereosinophilic syndrome (HES) and eosinophilic granulomatosis and polyangitis (EGPA)." (PMID 25709744, 2014). "Asthma is one of the airway hyperresponsive diseases which can be characterized by the accumulation of inflammatory cells, increase in mucus production, release of certain Th2 cytokines, IL-4, IL-5, and IL-13, and increased levels of IgE." (PMID 24936861, 2014). "Importantly, ADE genes showed interactions with other asthma-related genes such as IL5 and IL1B which are responsible for the immunological mechanisms of asthma and allergy." (PMID 24895604, 2014). "In addition, the associations of asthma with the IL5 C-703T polymorphism in Russians from the city of Tomsk and IL1B −511C>T in the Canadian Asthma Primary Prevention Study have been successfully replicated in our study." (PMID 24895604, 2014). "In addition, the IL-33/IL-5 signaling pathway plays a crucial role in the disease pathogenesis of severe asthma that is resistant to high doses of inhaled corticosteroids but responsive to systemic corticosteroids and anti-IL-5 therapy." (PMID 23613936, 2013). "In addition, Th2 lymphocytes play important role in initiation and progression of allergic diseases such as asthma through their ability to release interleukin (IL)-4 and IL-5." (PMID 23837463, 2013). "In an asthma model, IL-5-deficient mice did not display eosinophilia, airway hyperreactivity or pulmonary injury, in contrast to that observed in control mice." (PMID 23613936, 2013). "The primary role of IL-5 is thought to be for the development and maturation of an innate immune cell type, the eosinophil, which is also a culprit in allergic diseases such as asthma." (PMID 24068930, 2013). "In severe asthma, allergen sensitization and challenge increased Il6, Il5, and Il10 expression." (PMID 23781124, 2013). "Existing findings suggest measures of airway outcomes do not indicate improvements elicited by reduced eosinophilic airway inflammation, which have important implications for the choice of the outcomes in further clinical trials defining the potential utility of anti–IL-5 for asthma." (PMID 23544105, 2013).
asthma (continued). "In murine models of allergen-induced asthma, blockade of either IL-4 or its receptor has been shown to inhibit eosinophil influx into the airways and IL-5 release from T cells, as well as decreasing lung inflammation, serum IgE levels, and airway hyperresponsiveness to methacholine." (PMID 23853765, 2013). "Pinelliae rhizome and Citrus reticulata and their combinational prescription have deep inhibitory effects on airway inflammation in a murine model of asthma and it was mediated by suppression of Th2 cytokines (IL-4, IL-5, IL-13), IgE, eosinophil CCR3 expression in lung." (PMID 24367979, 2013). "Although beneficial during parasitic or helminth infection, IL-5 may have a detrimental role in the development and severity of asthma and allergic diseases." (PMID 24068930, 2013). "Further research is required to establish the possible role of anti–IL-5 as a therapy for asthma." (PMID 23544105, 2013). "Therapeutical interventions in allergic diseases such as allergen-induced asthma specifically targeting IL-4, IL-5 or IL-13 cytokines caused none to moderate improvement regarding disease severity and symptoms." (PMID 22853438, 2012). "The overall level of IL-5 in the CVA group was lower than that in the classic asthma group." (PMID 22927709, 2012). "OVA-treated mice showed significantly increased levels of IL-4 and IL-5 in both asthma models." (PMID 23189147, 2012). "Strategies aimed at the IL-5 dependent eosinophil recruitment into the airways or TNF-dependent airway hyperresponsiveness may hasten the resolution of asthma symptoms." (PMID 23043798, 2012). "Although IL-5 and IL-13 are known to be involved in the pathogenesis of asthma, no breast milk study has demonstrated associations with AS previously." (PMID 22805009, 2012). "Thus, IL-13 and IL-5 cytokines are considered to play a prominent role in the pathophysiology of asthma." (PMID 22805009, 2012). "Therefore, Th2 cells are important primarily in the airways, and Th2 cytokines such as interleukin (IL)-4, IL-5, and IL-13 play pivotal roles in the pathophysiology of asthma." (PMID 23244755, 2012). "Besides, the IL-5 levels in the CVA group decreased after treatment for 3 months while those in classic asthma group began to decrease after treatment for 6 months." (PMID 22927709, 2012). "IL-5 mobilizes eosinophils from the bone marrow pool and chemokines such as eotaxin-1 induce the recruitment of eosinophils into the airway of experimental asthma models." (PMID 22203879, 2012). "Additionally, Spred1 has been shown to negatively regulate IL-5-induced eosnophilia in a mouse model of asthma." (PMID 23166773, 2012). "Since 2001, several years after Leckie and colleagues reported their disappointing results with anti-IL-5, there have been over 4600 papers published with the keywords of “asthma” and “eosinophil” but less than 450 papers with the keywords “asthma” and “nerve”." (PMID 23150736, 2012). "One might speculate that blocking antibodies to ECP could be a symptom relieving addition to the already established GC and anti-IL5 therapies used in eosinophil rich asthma and other eosinophilic diseases." (PMID 21235798, 2011). "Gene profiling data of the current study revealed (i) a significant increase of IL13 mRNA levels in NP tissues, (ii) significant associations with the clinical parameters such as atopy and asthma, and (iii) a strong positive correlation between expression levels of IL13 and IL5." (PMID 21984922, 2011). "CD4+ NKT cells may also have a critical role in the pathogenesis of asthma and produce IL-5 when co-cultured with CD1d+ antigen presenting cells and IL-2." (PMID 21423619, 2011). "Cytokines such as IL-5, or chemokines such as eotaxin are produced in elevated levels and attract elevated numbers of eosinophils to the lumen and bronchi of the lungs in asthma, the nasal mucosa in allergic rhinitis and to the skin in atopic dermatitis." (PMID 21235798, 2011).
asthma (continued). "It has been shown that IL-4, IL-5 and IL-13, the well-defined Th2 cytokines, play an important role in the pathophysiology of allergic diseases including asthma These Th2 cytokines were significantly decreased in CC10-Smad7 mice compared to the wild type animals." (PMID 20405019, 2010). "A receiver operating characteristic (ROC) revealed a sensitivity of 67.1% for IL-12 (p40) and 66.5% for IL-5 and specificity of 66.7% for IL-12 (p40) and 58.3% for IL-5 serum levels to distinguish between the extrinsic and intrinsic asthma phenotype in children." (PMID 21179211, 2010). "Nevertheless our data is consistent with previous reports showing that over expression of IL-13 did not alter IL-5 expression in mouse lung, nor was it affected by IL-13 genetic deficiency in a mouse asthma model." (PMID 20573261, 2010). "To test our hypothesis we measured serum concentrations of eleven cytokines and chemokines that were recently described to play an important role in asthma pathogenesis: IL-4, IL-5, IL-8, IL-10, IL-12 (p40), IL-13, IL-17, TNFα, GM-CSF, eotaxin, and IFNγ." (PMID 21179211, 2010). "Such intervention may include IL-5 receptor antagonists, despite the fact that trials with IL-5 active drugs (in asthma) have been disappointing." (PMID 20144207, 2010). "The potential of Th2 cells to promote allergic immunopathology is amplified by production of a range of mediators including IL-4, IL-5, IL-9, IL-13 and IL-25 which together promote the salient feature of asthma such as IgE production, AHR, inflammation and tissue remodelling." (PMID 19769993, 2010). "PCR products for IL-5 and IL-13 amplified from lung cell RNA preparations were decreased in the PT, CR and their combinational prescription-treated mice compared with control mice (ova-induced asthma model mice group)." (PMID 19657453, 2009). "In addition, previous studies have shown that corticosteroids can suppress IL-4 and IL-5 release from peripheral blood cells of asthma patients in vitro and in vivo." (PMID 19436703, 2009). "The effects that we found cross-sectionally of interactions between chronic traffic-related air pollution and chronic stress on IL-5 production, total IgE levels, and eosinophil counts represent biologic pathways that have implications for clinical asthma outcomes." (PMID 18629323, 2008). "Thus heightened production of IL-5 along with elevated IgE and eosinophil counts suggests a biologic profile that is potentially detrimental for children with asthma in terms of vulnerability to symptoms." (PMID 18629323, 2008). "However, the results of recent clinical trials with monoclonal antibodies directed against IL-5 question the role of eosinophils in mediating the symptoms of asthma." (PMID 18315837, 2008). "Ten hub genes (including TNF, IL5, IL13, TLR4) were linked to 339 potential therapeutic agents; the exploratory network analysis highlighted overlap between predicted miRNA-regulated hub genes and existing asthma-relevant drug targets, including approved biologics." (PMID 42042546, 2026). "In over 60 patients with severe uncontrolled asthma who received anti-IL5/5R therapy, the baseline histopathologic score was a better predictor of response than T2 markers, indicating the potential benefits of tissue sampling to help guide therapy for patients with severe uncontrolled asthma." (PMID 40863432, 2025). "Additionally, measuring interleukin-5 or other inflammatory markers in exhaled air could be a promising new advancement for evaluating the asthma phenotype." (PMID 39860330, 2025). "In addition, in chronic asthma, Th2 cells are known to infiltrate the lungs and produce inflammatory cytokines, such as IL-4, IL-5, and IL-13, which are crucial in initiating and progressing allergic diseases, including asthma, by driving Th2-mediated immune responses." (PMID 40622480, 2025).
asthma (continued). "The results showed that IL-5 level and EOS percentage were significantly associated with the Simpson and Shannon index of BALF microbiota, rather than fecal microbiota, indicating that airway microbiota may have a closer connection with asthma progression." (PMID 39932326, 2025). "In particular, patients with SA who continue to present with persistent hypereosinophilia after receiving anti IL-5/5R-targeted biologic treatment or eosinophilia despite maintenance OCSs, should undergo a re-evaluation of the SA diagnosis before being requalified for further SA asthma treatment." (PMID 40508151, 2025). "For instance, tauroursodeoxycholic acid (TUDCA) significantly reduces HDM-induced IL-4, IL-5, IL-13, and IgE levels, whereas β-muricholic acid suppresses IL-6 and IL-33 production, underscoring the diverse metabolic pathways through which gut microbes influence asthma pathogenesis." (PMID 41229685, 2025). "Driven by T helper 2 (Th2) cells and T2 cytokines, such as interleukin 4 (IL-4), IL-5, and IL-13, the T2-high asthma endotype involves eosinophils, which may provide partial protection against COVID-19 by suppressing T1 inflammatory responses and cytokine storms." (PMID 40149651, 2025). "Bei Vorliegen eines komorbiden Asthmas und > 300 Eosinophilen/μl im Differenzialblutbild war IL‐5 in 98 % der Fälle nachweisbar, wohingegen das Fehlen eines komorbiden Asthmas sowie < 300 Eosinophile/μl nur in 50 % der Fälle mit dem Nachweis von IL‐5 verknüpft war." (PMID 40237828, 2025). "We show that IL-5 stimulation enhances extracellular matrix deposition, upregulates fibrotic mediators including collagen I, Fibronectin and Tenascin C, and promotes fibroblast cells survival, contributing to the persistent structural changes observed in asthma." (PMID 41188935, 2025). "In asthma, this relationship reflects converging type 2 pathways within the bronchial mucosa, driven by allergens and other environmental stimuli: local IL-4/IL-13 production induces iNOS and FeNO release, while IL-5 regulates eosinophil recruitment, maturation, and survival." (PMID 40981077, 2025). "In recent years, the use of monoclonal antibodies directed against interleukin-5 (anti-IL-5) and its receptor alpha (anti-IL-5R) has proven to be an effective therapeutic option for patients with severe asthma by reducing the number of eosinophils, which may promote disease remission." (PMID 40804423, 2025). "Furthermore, in vitro experiments demonstrated that UC-MSCs could directly reduce the secretion of IL-5 and IL-13 in Th2 cells and peripheral blood mononuclear cells (PBMCs) from mice model of asthma." (PMID 41309530, 2025). "The Re-Qualification of the asthma patient on Biologic therapy (ReQualBi) study has highlighted the importance of verifying prior diagnoses in patients with SA in whom HE persists despite therapy with anti-IL-5/5R MAbs, or in whom continued eosinophilia persists despite daily OCSs." (PMID 40508151, 2025). "Previous studies evidenced that IL-5 upregulates the levels of CD11b and CD44 on human eosinophils which, together with the increased serum IL-5 levels found in severe vs. mild asthma, could explain the upregulation of these markers in our cohort of SEA patients." (PMID 41394834, 2025). "In murine studies, the absence of IL-5 in deficient animals or the blockade of IL-5 with monoclonal antibodies led to improved symptoms of ovalbumin- or HDM-induced asthma, including airway remodeling, airway hyperresponsiveness and mucus production by airway epithelial cells." (PMID 41145900, 2025). "IL‐5 is essential for the recruitment and survival of eosinophils, while IL‐4 may contribute significantly to phenotypic or functional changes in asthma, such as airway hyperresponsiveness, eosinophil infiltration, and mucus overproduction, potentially exacerbating airway inflammation." (PMID 41159221, 2025).